CRP (C-reactive protein)
Diseases named in the same sentence as CRP in open-access papers (continued):
Sharing a sentence is not in itself a finding about the gene and the disease.
schizophrenia (continued). "Also we investigated associations between some immunological patterns and markers of inflammatory response (CRP, IL-2, IL-6, IL-10, the activity of LE and a1-PI, antibodies to S100B and MBP) with clinical symptoms in schizophrenia." (PMID 34025476, 2021). "On the other hand, few other studies have not found differences between serum CRP or IL-6 levels of patients with schizophrenia and control subjects." (PMID 34465310, 2021). "Early work demonstrated that inpatients with schizophrenia (n = 5) with CRP > 0.5 mg/dl had higher scores on the Positive and Negative Syndrome Scale (PANSS) negative symptom score than those inpatients with schizophrenia with CRP< 0.5 mg/dl (n = 21)." (PMID 32153436, 2020). "We measured plasma levels of systemic inflammation using CRP and compared these to measures of presumably GI-related biomarkers in individuals with schizophrenia with and without GI or endocrine disorders." (PMID 32625121, 2020). "A separate model for the sub-sample of patients diagnosed within the schizophrenia spectrum showed that change in CRP level did not predict T2–T4 change in the global cognitive performance as was found in the total sample (b=−0.01, p=0.208)." (PMID 30394240, 2019). "As CRP is produced by the liver when stimulated by cytokines such as TNF-α, these studies are in line with our finding of increased TNF-α levels in agitated patients with schizophrenia as well as in the general acute psychiatric population." (PMID 31509578, 2019). "CRP was significantly higher in people with GAD compared with controls, with a small effect size (Cohen’s d=0.38, 0.06–0.69), comparable with that reported in schizophrenia." (PMID 31326932, 2019). "Demographics, cognitive, symptom severity, negative emotional states, daily function measures, and C-reactive protein levels in chronically ill patients with schizophrenia and healthy controls." (PMID 30364161, 2018). "A large and recent study (n > 1,000) reported elevated levels of CRP in patients with schizophrenia compared to controls, with levels of CRP correlating both to positive and negative symptoms." (PMID 30766494, 2018). "This study is a pilot cross-sectional analysis investigating the relation of plasma CRP levels and the positive and negative symptoms of schizophrenia (the primary aim), assessed by the Positive and Negative Syndrome Scale (PANSS)." (PMID 29404313, 2017). "We did not have any data on history of infection around the time of blood collection, so possible confounding of the CRP-schizophrenia relationship by infection cannot be ruled out." (PMID 27622678, 2017). "About a third of adult schizophrenia and related psychosis cases were absent from the assessment at 15/16 years, so they did not have data on CRP levels at baseline." (PMID 27622678, 2017). "The quadratic term for CRP within the logistic regression model for CRP and schizophrenia was non-significant (P = 0.23), indicating no departure from linearity." (PMID 27622678, 2017). "Of note, prior studies have shown that the use of antipsychotic medications at the time of data collection does not significantly influence the levels of CRP in schizophrenia." (PMID 29404313, 2017). "This study found a positive correlation between plasma CRP and the negative symptoms of schizophrenia." (PMID 29404313, 2017). "Out of 6362 participants with CRP assessment at age 15/16 years, 88 were diagnosed with non-affective psychosis by age 27 years (1.38%), of which 22 were schizophrenia (0.35%)." (PMID 27622678, 2017). "Mean CRP levels at baseline were significantly different among groups with and without psychosis at follow-up; those with schizophrenia had higher CRP levels at baseline compared with the other groups." (PMID 27622678, 2017).
schizophrenia (continued). "This is the largest study to identify an association between raised CRP and vitamin D deficiency in established psychosis, with a similar inverse relationship between CRP and serum 25-OHD having been previously identified in schizophrenia patients in a case–control study." (PMID 27000113, 2016). "Dickerson, using a high-sensitivity CRP test (unlike conventional CRP testing as used in the present study), found elevated levels of CRP in patients with schizophrenia compared to healthy controls (p < 0.001)." (PMID 27547191, 2016). "Moreover, several studies have reported a positive correlation between serum CRP levels and negative symptoms, with patients with schizophrenia exhibiting more severe symptoms." (PMID 37728803, 2024). "Therefore, this study aims to explore the correlation between the effectiveness of SFN in ameliorating negative symptoms in schizophrenia patients and the levels of oxidative stress and CRP." (PMID 37728803, 2024). "However, when we searched for studies on cognitive impairment and our current parameters in schizophrenia, we could only find studies on NLR and CRP." (PMID 37763110, 2023). "Given that NF-κB kinases are necessary for forward propagation of the NF-κB signal from receptor to nucleus, it may appear counterintuitive that a subset of people with schizophrenia had downregulated peripheral expression of IKKβ and NIK transcripts but increased expression of IL-1β mRNA and CRP." (PMID 35027554, 2022). "However, the MR-PRESSO global test suggested that horizontal pleiotropy may have affected trans analyses of IL-1RA, sIL-2Rα, IL-17, CRP, BDNF, neutrophils and lymphocytes with schizophrenia only (all p<0.05)." (PMID 34280516, 2021). "We hypothesized that plasma CRP would positively correlate with the positive, negative, general psychopathology, and total psychotic symptoms of schizophrenia." (PMID 29404313, 2017). "Furthermore, the statistical test for interaction between CRP and sex in the logistic regression model of CRP and schizophrenia was not significant (P = 0.60)." (PMID 27622678, 2017). "To add to the relatively sparse literature evaluating the association between CRP and psychotic symptoms, we have carried out a cross-sectional analysis of plasma CRP levels and positive and negative symptoms in a pilot sample of 39 patients with schizophrenia." (PMID 29404313, 2017). "This showed that 9 of the analytes (C-reactive protein, cortisol, resistin, TIMP-1, chromogranin A, VEGF, thrombopoetin, alpha-2 macroglobulin, and glutathione S-transferase) were also found to be reproducibly altered between schizophrenia and control subjects in serum." (PMID 23118852, 2012). "Thus, alterations in the NF-κB activation pathway may be upstream of changes in circulating immune biomarkers such as inflammatory proteins and CRP in (what appears to be) non-infective inflammation in people with schizophrenia." (PMID 35027554, 2022). "Interestingly, a recent meta-analysis reported that CRP levels were increased in patients with schizophrenia but is not altered by antipsychotic medication, notwithstanding whether these were typical or atypical antipsychotics." (PMID 35800023, 2022). "Therefore, the hypothesis in the conclusion of the Article—that medications which reduce CRP levels can be used in schizophrenia—is not supported." (PMID 29465083, 2018). "In summary, our real-world findings demonstrate that peripheral markers such as CRP, NLR, MLR, and SII do not accurately reflect symptom severity in patients with schizophrenia." (PMID 40980040, 2025). "As such, we tested the inflammatory marker CRP, and complement system including C3, C4 and CFH between schizophrenia patients with or without anhedonia." (PMID 37520223, 2023).
schizophrenia (continued). "The presence of a significant difference in cognitive variables between elevated and normal CRP groups in schizophrenia coupled with the lack of significant cognitive differences in the healthy sample also supports the hypothesis suggesting a role of inflammatory processes in schizophrenia." (PMID 30364161, 2018). "Path-analysis was used to evaluate direct and indirect relationships between Childhood Trauma Questionnaire (CTQ) scores, serum concentrations of C-reactive protein (CRP), interleukin (IL)-6 and tumour necrosis factor (TNF)-α, and Positive And Negative Syndrome Scale of Schizophrenia (PANSS) scales." (PMID 41049865, 2025).
Cognitive impairment (241 papers, 2009 to 2026). Abnormal cognition is characterized by deficits in thinking, reasoning, or remembering. "In our study, both D-dimer and CRP were also associated with CF, suggesting common pathways involved in the development of frailty and cognitive impairment in people with HIV." (PMID 40971458, 2026). "Among the dysregulated markers, recent evidence further suggests an association between cognitive impairment and abnormal levels of C-reactive protein (CRP), interleukin-1 receptor antagonist (IL-1RA), IL-6, and TNF-α, along with their respective receptors." (PMID 40797218, 2025). "A large body of cross‐sectional research has demonstrated that higher serum CRP levels are associated with MDD as well as its core clinical features such as cognitive impairment and sleep disturbance." (PMID 41014304, 2025). "The distinct biological profiles observed in the SIC and GIC groups – characterised by differences in BDNF and CRP levels – highlight the complexity of the mechanisms underlying cognitive impairments in bipolar disorder." (PMID 41367212, 2025). "While previous studies have reported associations between serum CRP level and cognitive impairment under various conditions, our research is the first one showing the adverse effects of serum hs-CRP level on the cognitive function of ALS patients." (PMID 39290715, 2024). "In contrast, high-sensitivity-C-reactive protein is recognized as a risk biomarker for cerebrovascular disease, which can lead to pathological damage and cognitive impairment, thus increasing the risk of developing VD." (PMID 39335481, 2024). "Interleukin-6 (IL-6), tumor necrosis factor-a (TNF-a), and C-reactive protein have been shown to be linked to cognitive impairment, and changes in peripheral CD4+, CD8+, CD3+, and CD4+/CD3+ levels have been documented." (PMID 38322584, 2024). "Overall cognitive impairment at year 2 was associated with high (> 3 mg/L) baseline CRP (OR = 2.84, 95%CI: 1.06–7.64, p = 0.037)." (PMID 38840166, 2024). "Cognitive impairment has been closely linked to inflammation, as shown by elevated levels of C-reactive protein (CRP), interleukin (IL)-6, and tumor necrosis factor (TNF)-α in affected individuals." (PMID 39118546, 2024). "Models of the initial approach demonstrated an association between overall cognitive impairment at year 2 and baseline levels of IL-8 (OR = 0.85, 95%CI: 0.72–0.98, p = 0.02), as well as CRP (OR = 2.8, 95%IC: 1.10–7.66, p = 0.03)." (PMID 38840166, 2024). "Raised fibrinogen was only associated with post-acute cognitive deficits when raised relative to CRP." (PMID 37653345, 2023). "For instance, someone with high fibrinogen and high D-dimer relative to CRP would tend to score high on both dimensions and would be at higher risk of objective and subjective cognitive deficits and occupational impact." (PMID 37653345, 2023). "Cognitive impairment per se appears to be associated with higher RA disease activity, with increased CRP levels representing one of the core components of the 28-joint Disease Activity Score (DAS-28) and a widely used marker of RA activity and progression." (PMID 36776896, 2023). "IL-6 and CRP levels are associated with cognitive impairment, executive function, and attention/working memory." (PMID 37762207, 2023). "During a median of 5.79 years follow-up, the highest quartile of the Hs-CRP group showed a faster rate of cognitive decline (−0.0053 SD/year, p = 0.006) and a higher risk of cognitive impairment (HR 1.0814, p = 0.044) than those in the lowest quartile." (PMID 37190623, 2023). "Analyses of HUNT4 have further shown that shift work is associated with higher levels of C-reactive protein and chronic musculoskeletal pain, and that cognitive impairment is associated with lower physical performance." (PMID 35578897, 2023). "Cytokines were associated with cognitive impairment in patients, and C-reactive protein (CRP) levels were inversely correlated with cognitive and functional decline." (PMID 35163141, 2022).
Cognitive impairment (continued). "A cross-sectional study evaluated the association between CRP levels, depressive symptoms, and cognitive impairment in 149 MDD patients treated with antidepressants for six weeks." (PMID 35163538, 2022). "Even in patients with mild TBI, increased baseline CRP was associated with persistent post-concussion syndrome and persistent cognitive impairment." (PMID 35547639, 2021). "Elevated serum levels of proinflammatory cytokines, including interleukin 6 (IL-6), tumor necrosis factor-alpha (TNF-α), and C-reactive protein, can cause cognitive impairment." (PMID 33627087, 2021). "The brain's immune response to mild TBI is also evident in the blood, as elevated c-reactive protein (CRP) levels at admission are independently associated with the increased risk of persistent psychological problems and cognitive impairment." (PMID 33679762, 2021). "High-sensitivity C-reactive protein (hs-CRP) is an indicator of inflammation and plays an important role on overweight-associated cognitive impairment." (PMID 33363509, 2020). "In-hospital death was associated with higher age, longer hospital stay, cognitive impairment, and clinical and laboratory indicators of more severe disease (higher prevalence of dyspnea on admission, higher C-reactive protein and LDH, lower PaO2/FiO2)." (PMID 33034016, 2020). "CRP has been associated with subsequent cognitive impairment and age-related cognitive decline, whereas the E4 allele, which was associated with low CRP, increases the risk of cognitive reduction and Alzheimer disease." (PMID 32646381, 2020). "In recent years, several studies tried to elucidate the mechanisms underlying cognitive impairment in SZ, with a number of studies testing the association between CRP levels and cognitive performance in SZ patients." (PMID 32994460, 2020). "Inflammatory markers, such as high sensitivity C-reactive protein (hs-CRP), and cognitive impairment (CI) are associated with mortality; CRP is related to the deterioration of CI." (PMID 31832073, 2019). "Our findings demonstrated that associations between mid‐life baseline IL‐6 and CRP with later life cognitive impairment were explained by educational attainment and modifiable life course factors." (PMID 31328177, 2018). "Abnormal CRP has been associated with a wide range of cognitive impairment in SZ stabilized individuals." (PMID 30190688, 2018). "In light of these issues, the current study sought to investigate associations between inflammation, cognitive impairments, and emerging psychopathology in childhood, utilising salivary CRP as a marker of inflammation." (PMID 28694011, 2017). "These authors reported that elevated levels of plasma CRP were significantly associated with mild cognitive impairment." (PMID 26865259, 2016). "Other researchers had found serum levels of CRP were associated with cognition impairment and inversely correlated with MMSE and MoCA scores." (PMID 26578953, 2015). "A meta-analysis that evaluated associations between CRP and cognitive deficit found that older men are more susceptible to elevated concentrations of CRP than elderly women." (PMID 24587705, 2014). "We found that elevated serum levels of CRP were associated with worse cognitive function and an increased risk of cognitive impairment in people aged 50 and older." (PMID 24587705, 2014). "Recent work has explored the relationship of inflammation and cognitive function indicating an inverse association of levels of interleukin-6 and CRP with incident cognitive impairment, with mixed results regarding rate of change in cognitive function." (PMID 19638207, 2009). "Specifically, there was a significant positive correlation with P3b, indicating that patients with elevated CRP levels may be at risk for a more severe cognitive impairment." (PMID 40673224, 2025). "CRP levels fluctuate in response to change in inflammatory status and may be used to infer whether low-grade systemic inflammation is associated with cognitive impairment." (PMID 39354711, 2024).